DPP4 (dipeptidyl peptidase 4)
Diseases named in the same sentence as DPP4 in open-access papers (continued):
Sharing a sentence is not in itself a finding about the gene and the disease.
Hypoglycemia (continued). "It is worth noting, however, that a reduction in the dose of SU according to the recommendation and labeling was usually performed when a DPP-4 inhibitor was added, to reduce the risk of severe hypoglycemia." (PMID 24300302, 2012). "Because the glycemic effects of DPP-4 inhibitors are glucose dependent and decline as postprandial serum glucose levels return to normal ranges, they are less likely to cause hypoglycemia." (PMID 22248301, 2012). "The use of dipeptidyl peptidase-4 (DPP-4) inhibitors increases the risk of hypoglycemia, but importantly, DPP-4 inhibitors reduce the hypoxia-induced upregulation of the pro-oxidant enzyme, nicotinamide adenine dinucleotide phosphate oxidase, in rat cardiomyocytes." (PMID 41020857, 2025). "In addition, DPP4 inhibitors have shown a neutral effect in most CV outcome trials, and they have a moderate effect in reducing HbA1c with a low risk of hypoglycemia similar to SGLT2 inhibitors." (PMID 39919084, 2025). "Our findings suggest that, for pre‐dialysis patients with T2DM, DPP‐4 inhibitors may provide more renal advantages and less hypoglycemia risk than meglitinides." (PMID 40611400, 2025). "Furthermore, DPP-4 inhibitors are recommended for older individuals with T2D due to their CV safety, negligible risk of hypoglycemia, and minimal adverse effects." (PMID 40471298, 2025). "Although the clinical significance of the interaction between OADMs and CPA remains unclear, caution may be warranted when combining CPA with OADMs, particularly DPP-4 inhibitors, because of the potential risk of morning hypoglycemia." (PMID 41464548, 2025). "Additionally, use of high‐affinity sulfonylureas was associated with a 3.48‐fold (95% CI, 2.67–4.55) increased risk of hypoglycaemia and a 31% (HR, 1.31; 95% CI, 1.22–1.40) increased risk of all‐cause mortality compared to DPP‐4 inhibitors." (PMID 41017568, 2025). "Furthermore, DPP-4 inhibitors play a significant role in the regeneration and differentiation of pancreatic cells and are well-tolerated, reducing the risk of hypoglycemia and cardiovascular side effects." (PMID 40066124, 2024). "Furthermore, for enhanced glycemic control with a lower risk of hypoglycemia, options like incretin agents (DPP4 inhibitors or GLP1-RAs), SGLT2 inhibitors, acarbose, or pioglitazone were suggested as add-on therapies." (PMID 39906353, 2024). "Additionally, although DPP-4 inhibitors are less likely to cause hypoglycemia, the risk of hypoglycemia with DPP-4 inhibitor use in patients with DM1, where hypoglycemia is observed even in untreated cases, has not yet been clarified." (PMID 39274465, 2024). "In both RCTs (pooled relative risk: 0.56; 95% confidence interval: 0.44–0.72) and observational studies, the usage of DPP-4 (Dipeptidyl peptidase inhibitor-4) inhibitors was linked to a lower incidence of feeling hypoglycemia during Ramadan (pooled relative risk: 0.27; 0.09–0.75)." (PMID 38169925, 2023). "This may be attributable to the selection of newer drug generations with a lower risk of hypoglycemia, albeit higher costs, including dipeptidyl peptidase-4 inhibitors, sodium-glucose cotransporter-2 inhibitors and glucagon-like peptide-1 agonists." (PMID 37046876, 2023). "Moreover, in hospitalized patients, treatment with DPP-4 inhibitors has been associated with similar glycemic control, and lower rates of hypoglycemia compared with insulin regimens." (PMID 36964858, 2023). "However, treatment with GLP-1 RA and DPP-4 inhibitors in hospitalized patients has been associated with similar glycemic control and lower rates of hypoglycemia compared with insulin regimens." (PMID 36964858, 2023). "Furthermore, the risk of severe hypoglycemia is extremely low when DPP-4 inhibitors are administered alone." (PMID 36078917, 2022). "We found that the addition of DPP-4 inhibitors in older patients with ‘inadequate’ glycaemic control may increase mortality and increases the risk of experiencing hypoglycaemia compared with standard care." (PMID 35111291, 2022).
Hypoglycemia (continued). "Dipeptidyl-peptidase-4 inhibitors (DPP4i) have been the most used antidiabetic medications worldwide due to their good safety profiles and tolerability with a low risk of hypoglycemia, however, large cardiovascular outcome trials (CVOTs) have not shown any significant the prognostic superiority." (PMID 35332212, 2022). "There are several reasons for this low risk of hypoglycemia with DPP-4 inhibitors." (PMID 31275243, 2019). "Furthermore, in several meta-analyses and observational studies, DPP-4 inhibitors were reported to be associated with an increased risk of worsening heart failure, besides acute pancreatitis and hypoglycemia." (PMID 30961600, 2019). "The DPP-4 inhibitors were also found to have a low risk of adverse events, including hypoglycemia." (PMID 31275243, 2019). "A consisting finding with DPP-4 inhibition has been its low risk for hypoglycemia." (PMID 31275243, 2019). "All authors concluded that no serious side effects were confirmed to be clearly related to the DPP-4 inhibitors, including hypoglycemia, and other causes led to discontinuation from further participation; in addition, ketoacidosis and pancreatitis were not reported." (PMID 29507862, 2018). "In the present study, increase of insulin secretion by DPP-4 inhibitors via night hyperglycemia might cause fasting hypoglycemia in the morning." (PMID 30285859, 2018). "Moreover, sulfonylureas as a second-line agent have a greater risk of severe hypoglycemia than DPP-4 inhibitors and SGLT-2 inhibitors." (PMID 29527102, 2018). "In contrast, those with higher frailty severity, possibly due to their increased risk of hypoglycemia, were less likely to receive multiple OADs including biguanides, sulfonylurea, α-glucosidase inhibitors, thiazolidinediones, and dipeptidyl peptidase 4 inhibitors." (PMID 30261879, 2018). "Dipeptidyl peptidase-4 (DPP-4) inhibitors, which inhibit the degradation of active incretins including glucagon-like polypeptide-1 (GLP-1) by DPP-4, increase the concentration of active incretins and thereby improved glycemic control with low hypoglycemia risk." (PMID 29402270, 2018). "However, there are no comparative studies on the effects of SGLT2 inhibitors and DPP4 inhibitors on HbA1c, body weight and hypoglycemia as risk factors of cardiovascular diseases." (PMID 29895330, 2018). "Results from both pair-wise as well as network meta-analysis of RCTs and observational studies suggest that the use of incretin mimetics, specifically DPP-4 inhibitors were associated with the lowest incidence and rate of hypoglycemia, when compared with sulfonylureas." (PMID 26765440, 2016). "First, DPP4 inhibitors may cause hypoglycemia, particularlyin combination with other hypoglycemic agents." (PMID 27460913, 2016). "The risk of hypoglycemia for patients using DPP-4 inhibitors was the smallest." (PMID 26566411, 2015). "When combined with sulphonylurea, DPP-4 inhibitions showed increased risk of hypoglycaemia." (PMID 24917890, 2014). "Since DPP-4 inhibitors are associated with a lower incidence of hypoglycemia compared to conventional hypoglycemic drugs, they have been suggested to improve the mortality of patients with T2DM because they can enforce strict glycemic control without causing fatal hypoglycemia." (PMID 24428883, 2014). "The good safety and tolerability of the GLP-1R agonists and DPP-4 inhibitors are well documented leading the AACE/ACE guidelines to conclude that the GLP-1R agonists are safer than sulfonylureas or glinides with respect to the risk of hypoglycemia." (PMID 22390369, 2012). "Because the action of GLP-1 on insulin secretion is strictly glucose dependent, the risk of hypoglycaemia associated with DPP-4 inhibitors is low.The main elimination route of the first generation of approved DPP-4 inhibitors (sitagliptin, saxagliptin, vildagliptin) is via the kidney." (PMID 22125632, 2011).
Hypoglycemia (continued). "Moreover, DPP‐4 inhibitors were shown to associate with a lower incidence of hypoglycemia and gastrointestinal side effects, rendering them an important alternative in cases of metformin intolerance or hypoglycemia concerns." (PMID 41521023, 2026). "Additionally, glipizide should be substituted with α-glucosidase inhibitors, dipeptidyl peptidase-4 inhibitors, sodium-glucose co-transporter-2 inhibitors, or other medications with a lower hypoglycemia risk, especially when administering diclofenac for fractures." (PMID 40355187, 2025). "When there is a compelling need, in other subjects, to minimize the risk of hypoglycemia, DPP-4 inhibitors, thiazolidinediones, SGLT2 inhibitors, or GLP-1 receptor agonists may be added, except when cost is a major issue, in case thiazolidinediones or sulfonylureas could be given." (PMID 31275243, 2019). "Furthermore, even DPP-4 inhibitors, its use combined with SU agents could cause severe hypoglycemia, and also reported that the incidence frequency of severe hypoglycemia changes based on the type of SU used in the combination." (PMID 26566411, 2015). "A risk for hypoglycemia might exist when linagliptin, as well as another DPP-4 inhibitor, is used as a treatment adjunctive to an insulin secretagogue, and an initial dose decrease in background secretagogue medication should be considered to prevent hypoglycemic events." (PMID 26075286, 2015). "On the other hand patients receiving DPP-4 inhibitors (OR 0.34; 95%CI 0.16-0.70), thiazolidinediones (OR 0.50; 95%CI 0.28-0.89) and as a trend glucosidase inhibitors (OR 0.22; 95%CI 0.03-1.60) on top of metformin had a decreased risk for hypoglycaemia in univariate analyses." (PMID 21756359, 2011). "However, due to the insulin-sensitizing effects of DPP-4 inhibitors and the inherent risk of hypoglycemia associated with premixed insulin, we hypothesize that the combination of vildagliptin and premixed insulin may lead to an increased likelihood of hypoglycemic episodes." (PMID 40620795, 2025). "However, the risk of hypoglycemia varies among different oral medications; for example, sulfonylureas and meglitinides are associated with a higher risk of hypoglycemia, whereas agents like metformin, DPP-4 inhibitors, and SGLT-2 inhibitors have a lower hypoglycemic risk." (PMID 40959330, 2025). "Except for hypoglycaemia, the incidence rates of primary and secondary outcomes were comparable between the low‐affinity mitoKATP channel sulfonylurea group and DPP‐4 inhibitor group." (PMID 41017568, 2025). "In cases of mild, moderate, or severe hypoglycemia, DPP-4 inhibitors were preferred over sulphonylureas due to their more favorable safety profile." (PMID 40574081, 2025). "Combined treatment with DPP4 and SGLT2 inhibitors has been proposed as an effective treatment option for T2DM given their complementary mechanisms of action and low risk of hypoglycemia or weight gain." (PMID 38223523, 2024). "There were no hypoglycemic events in either group, which is in accordance with the low risk of hypoglycemia noted for metformin, SGTL2 inhibitors, and DPP4 inhibitors." (PMID 38223523, 2024). "Compared to utilizing sulphonylureas, the results demonstrated that using DPP-4 inhibitors significantly lowers the incidence of hypoglycemia, with an odds ratio of 0.38 (95% confidence interval: 0.26 to 0.55, p value 0.00001)." (PMID 38169925, 2023). "Earlier studies reported that DPP4 inhibitors are widely used for the treatment of T2DM as they have negligible risk factors, such as hypoglycemia, and are well tolerated in the systemic circulation." (PMID 36839456, 2023). "Linagliptin and other DPP-4 inhibitors suppress DPP-4, a peptidase which cleaves hypoglycemia incretins secreted by intestinal L cells such as glucagon-like peptide (GLP)-1, thereby lowering the post-prandial blood glucose level." (PMID 35328486, 2022).
Hypoglycemia (continued). "Antidiabetic drugs such as metformin, acarbose, thiazolidinediones (TZDs), GLP-1 RAs, and dipeptidyl peptidase-4 (DPP-4) inhibitors work in a glucose-dependent manner and generally have a low risk of hypoglycemia." (PMID 36225474, 2022). "DPP-4 inhibitors have a greater reduction in HbA1C than in fasting blood sugar, which can lower the possible side effect of hypoglycemia and reduce blood glucose variability." (PMID 34496858, 2021). "Overall, these studies show that DPP-4 inhibitors can improve hypoglycemia/hyperglycemia and BG levels in T2DM patients." (PMID 34203048, 2021). "She had previously experienced severe hypoglycemia in the event of an overdose of her mother’s medicine including an SGLT2 inhibitor along with a dipeptidyl peptidase-4 inhibitor and a sulphonylurea." (PMID 31918741, 2020). "Dipeptidyl peptidase-4 (DPP-4) inhibitors, offer a glucose lowering therapy with a reportedly low risk of hypoglycemia and they have been associated with less glycemic variability." (PMID 32256448, 2020). "Another new hypoglycemic drugs, dipeptidyl-peptidase 4 (DPP4) inhibitors, combined with metformin therapy improved glucose level with a significantly greater reduction in GV and hypoglycemia." (PMID 32622354, 2020). "Since DPP-4 inhibitors and SGLT2 inhibitors have such different mechanisms of action and the risk of hypoglycaemia with both medications is pretty low, it seems that the combination therapy of both inhibitors is very promising." (PMID 32337293, 2020). "Of the insulin users of the hypoglycemia group, 2 patients used an insulin mixture and 1 patient was on intensive insulin therapy combined with DPP-4 inhibitor therapy." (PMID 30815039, 2019). "Long-term treatment with GLP-1 analogs disturbs glucose homeostasis, and combination therapy of sulfonylurea and DPP4 inhibitors (that elevate cAMP) has been shown to lead to severe hypoglycemia, an effect that likely depends on Epac." (PMID 31099751, 2019). "In four of the studies there was a slightly increased rate of hypoglycemia episodes in the combination with DPP-4 inhibitor and sulfonylura compared to sulfonylurea alone." (PMID 31275243, 2019). "Furthermore, a reduction in the dose of sulfonylureas is usually recommended when a DPP-4 inhibitor is added, because of a pharmacodynamic interaction (rather than a pharmacokinetic interaction) between the sulfonylurea and the DPP-4 inhibitor, which may result in a higher risk of hypoglycemia." (PMID 31366085, 2019). "Treatment of GC-DM was necessary for at least 1 month after GC-DM developed, and fasting hypoglycemia in early morning should be monitored after 2 weeks of GC therapy with DPP-4 inhibitors." (PMID 30285859, 2018). "For instance, compared to sulfonylureas and meglitinides, dipeptidyl peptidase-4 (DPP-4) inhibitors provide important reduction in HbA1c concentration, with a low risk for hypoglycemia, even in advanced CKD patients (eGFR < 30 mL/min per 1.73 m2)." (PMID 29209216, 2017). "The use of DPP-4 inhibitors in patients with T2DM has markedly increased in clinical practice because these are generally weight neutral and have a low risk of hypoglycemia." (PMID 29057274, 2017). "Recently developed drugs, such as dipeptidyl peptidase-4 (DPP4) and sodium-glucose co-transporter-2 (SGLT2) inhibitors, are expected to have cardiovascular benefits owing to the low risk of hypoglycemia and weight gain." (PMID 28542373, 2017). "While DPP-4 inhibitor and time-varying ESRD predicted a lower risk of death, factors such as age, male gender, insulin use, hypoglycemia and other baseline comorbidities all predicted mortality." (PMID 29100450, 2017). "Omarigliptin was generally well tolerated, with an incidence of hypoglycemia that was consistent with the experience with other DPP-4 inhibitors." (PMID 28893244, 2017). "Rates of hypoglycemia in both the SAVOR andEXAMINE trials were modestly increased in patients taking DPP4 inhibitors." (PMID 27460913, 2016).
Hypoglycemia (continued). "DPP-4 inhibitors showed OR less than 1 as 0.86, which was statistically significant; this suggested that incidence of hypoglycemia was low in patients using DPP-4 inhibitors." (PMID 26566411, 2015). "This shows that DPP-4 inhibitors are effective at preventing hypoglycemia and have a lower incidence of adverse events than other OHAs." (PMID 26566411, 2015). "Data revealed that the DPP-4 inhibitor group had a lower incidence of hypoglycemia than did the glipizide group (551 participants, random RR 0.40, 95%CI 0.23 to 0.69; p = 0.0009; there was no heterogeneity (I2 = 0%; p = 0.42)." (PMID 25360775, 2014). "Both dapagliflozin and the DPP-4 inhibitors demonstrated statistically significant lower odds of hypoglycaemia compared to GLP-1 analogues (0.16 [95% CrI: 0.03, 0.65] and 0.17 [95% CrI: 0.04, 0.64] respectively)." (PMID 25006351, 2014). "The definition of hypoglycaemia was broadly similar between studies (requiring symptomatic confirmation) with the notable exception of one of the three DPP-4 inhibitor studies." (PMID 25006351, 2014). "The addition of DPP-4 inhibitors to ongoing insulin therapy is expected to reduce insulin dosage, leading to a reduction in the frequency of hypoglycaemia and/or weight gain." (PMID 24607023, 2014). "On the other hand, insulin sensitisers (glitazones) and incretin based therapies (DPP-4 inhibitors, GLP-1 analogues) have been associated with a low risk of hypoglycaemia." (PMID 23075070, 2012). "The incidence of hypoglycemia with DPP-4 inhibitors has been low, but is higher in patients also using sulfonylurea." (PMID 21707956, 2012). "In this study, we evaluated the effectiveness of risk minimization activities in Japan intended to avoid severe hypoglycemia by reducing the SU daily dose when adding a DPP-4 inhibitor." (PMID 24300302, 2012). "On the contrary, glitazones (0.55; 0.35-0.86), DPP-4 inhibitors (0.57; 0.43-0.76) and GLP-1 analogues (0.48; 0.28-0.81) were associated with a reduced risk of hypoglycaemia." (PMID 23075070, 2012). "On the contrary, glitazones, DPP-4 inhibitors and GLP-1 analogues were associated with a reduced risk of hypoglycaemia." (PMID 23075070, 2012). "Sitagliptin, a dipeptidyl peptidase-4 (DPP-4) inhibitor, has been shown to be effective and well tolerated with a low incidence of hypoglycaemia in clinical trials up to 2 years in duration." (PMID 21951832, 2011). "Compared to baseline the use of sulfonylureas in patients with hypoglycaemia was strongly reduced (-25.9%), while in a significant proportion of patients DPP-4 inhibitors (+26.8%), GLP-1 analogs (+7.6%) and insulins (+26.6%) were introduced." (PMID 21756359, 2011). "Clearly, however, treatment with a DPP-4 inhibitor (sitagliptin or vildagliptin) reduces the incidence of hypoglycaemia relative to treatment with a sulphonylurea agent during Ramadan." (PMID 21951832, 2011). "Unlike sulfonylureas, DPP-4 inhibitors pose less risk of hypoglycemia and are safer in insulin pump regimens." (PMID 41590243, 2026). "Dipeptidyl peptidase-4 (DPP-4) inhibitors enhance the action of endogenous incretins, leading to a modest HbA1c reduction of 0.5–1.0%, with a neutral effect on body weight and a low risk of hypoglycemia." (PMID 41471118, 2025). "For these patients, DPP-4 inhibitors remain a cornerstone therapy, as they effectively enhance insulin secretion without increasing the risk of hypoglycemia." (PMID 40607140, 2025). "If needed to achieve glycemic goals, use of anti-diabetic agents showing potential CV benefits (e.g., metformin, pioglitazone) or proven CV safety (e.g., DPP-4 inhibitors, lixisenatide, exenatide, insulin, glimepiride) with lower risks of hypoglycemia is recommended." (PMID 41299307, 2025). "These DPP-4 inhibitors have the advantages of definite hypoglycemic effects, a low risk of hypoglycemia, no weight gain, good cardiovascular safety, and once-daily administration." (PMID 38792165, 2024).